IGF1 (insulin like growth factor 1)
Diseases named in the same sentence as IGF1 in open-access papers (continued):
Sharing a sentence is not in itself a finding about the gene and the disease.
lung carcinoma (continued). "However, so far, the relationship between circulating IGF-1 and lung diseases such as asthma, chronic obstructive pulmonary disease (COPD), lung cancer and idiopathic pulmonary fibrosis (IPF) remains unclear, and the available data cannot infer causality." (PMID 36936149, 2023). "Interestingly, despite the lack of epidemiological as well as clinical studies of circulating IGF-1 in relation to lung disease, substantial preclinical evidence has revealed the potential effects of IGF-1 in the pathobiology of asthma, COPD, lung cancers, and IPF." (PMID 36936149, 2023). "For example, severe bronchial dysplasia produces more paracrine and autocrine IGF-1 than benign bronchial epithelial cells, which then interacts with tobacco carcinogens to promote lung carcinogenesis, thereby implying an early role of IGF-1 in the development of lung cancers." (PMID 36936149, 2023). "Interestingly, the IGF axis is a complex molecular network (including peptide‐ligands IGF1, IGF2, and insulin, and the receptors IGF1R, IGF2R, and INSR) that is involved in a wide variety of neoplasms such as prostate, breast, colorectal, and lung cancers." (PMID 34668636, 2022). "It is therefore possible that cigarette‐related carcinogen exposure may overshadow the more subtle effects of IGF‐1 on cancer development, which could explain the general lack of an association between IGF‐1 and risk of lung cancer." (PMID 27734632, 2016). "Indeed, insulin and IGF-1 not only stimulated TRB3 expression in human HepG2 cells in time-dependent and concentration-dependent manners by activating TRB3 transcription 17, but also enhanced TRB3 expression in human colon and lung cancer cells." (PMID 26268733, 2015). "Similarly, insulin and IGF-1, no matter they activate or not the autophagic signals, induced a significant accumulation of insoluble p62 in human liver, colon and lung cancer cells." (PMID 26268733, 2015). "Further studies on the function of TM4SF4 in lung cancer cells can be started based on the interaction of TM4SF4 with other molecules, such as integrins, growth factor receptors, and cytoplasmic components, which might reveal the mechanism of IGF1 induction." (PMID 25344917, 2014). "Nonsmokers carrying the IGF1 X/X genotype had an OR of 1.29 (95% CI = 0.78–2.15) for lung cancer." (PMID 22347413, 2012). "In keeping with this speculation, we observed that heavy smokers with susceptible IGF1, IGF2, and IGFBP3 genotypes had an elevated risk of lung cancer, although the interaction effect was not significant." (PMID 22347413, 2012). "It indicated that neither the circulating level of IGF-1 nor that of IGFBP-3 could act as long-term(the follow-up period were all more than five years and some even more than twenty years in the prospective studies we included in this meta-analysis)predictor of lung cancer." (PMID 23185474, 2012).
Alzheimer disease (154 papers, 2010 to 2026). A progressive, neurodegenerative disease characterized by loss of function and death of nerve cells in several areas of the brain leading to loss of cognitive function such as memory and language. "While an elevated level of homocysteine is associated with impaired cognition and Alzheimer’s disease, IGF-1 is known to have a favorable effect on neuronal growth and cognitive performance." (PMID 40517239, 2025). "The risk and development of cognitive diseases, including dementia and Alzheimer’s disease, have been associated with levels of IGF-1." (PMID 38858326, 2024). "In the brain of Alzheimer’s disease patients, bioavailable IGF-1 deficiency was shown with increases in bound IGFBP-3 and bound cGP." (PMID 35631301, 2022). "Attenuating acetylcholinesterase and insulin/insulin-like growth factor-1 signaling in the hippocampus is associated with Alzheimer’s disease (AD) development." (PMID 35892598, 2022). "For instance, reduced IGF-1 signaling delays age-associated proteotoxicity in a mouse model of Alzheimer disease." (PMID 32832002, 2020). "Such information is important because Alzheimer’s disease (AD) has been associated with lower serum levels of IGF-1 and BDNF." (PMID 32192537, 2020). "The following keywords have been used: “GH/IGF-1” associated with “neuroregeneration”, “amyotrophic lateral sclerosis”, “Alzheimer disease”, “Parkinson’s disease”, “brain”, and “neuron”." (PMID 29149058, 2017). "For example, systemic injections of IGF-1 mimicked some of the effects of exercise in the brain, and genetically reduced IGF-1 signaling in the whole organism reduced inflammation and neuronal loss in a mouse Alzheimer disease model." (PMID 28902870, 2017). "Disrupted insulin/IGF-1 signaling is implicated in Alzheimer's disease, among other conditions, yet its specific influence on glutamate receptor-mediated calcium responses remains unclear." (PMID 41993473, 2026). "Lower levels of IGF1 have been associated with an increased risk of developing Alzheimer’s disease." (PMID 38809924, 2024). "IGF-1 has been implicated in neurodevelopment, both prenatally and in the early post-natal period, and in plasticity and remodeling throughout life, and adiponectin seems to play a role in the onset of cognitive decline and in Alzheimer’s disease." (PMID 32748851, 2020). "In fact, recent studies have shown that Klotho might prevent the development of Alzheimer's disease associated with aging by inhibiting insulin/IGF-1 signaling and, consequently, oxidative injury in the brain." (PMID 26599613, 2015). "Furthermore, studies suggest that increasing IGF-1 levels in the body could slow down or improve cognitive decline associated with Alzheimer’s disease." (PMID 38858326, 2024). "Defective brain insulin signalling, as well as related signalling by insulin-like growth factor 1 (IGF-1), is associated with neurological disorders, including Alzheimer’s disease, suggesting that cognitive impairment could be related to a state of brain insulin resistance." (PMID 34573112, 2021). "Finally, recent studies also suggest that Klotho might prevent the development of Alzheimer's disease (AD) associated with aging, probably by inhibiting insulin/IGF-1 signaling and, consequently, oxidative injury in the brain in a murine model of AD." (PMID 26599613, 2015). "Elevated levels of IGF-1 have been associated with improved executive function and attention in individuals with mild cognitive impairment (MCI) and Alzheimer’s disease (AD)." (PMID 40699632, 2025). "Alzheimer’s disease (AD) is characterized by impaired insulin/insulin-like growth factor-1 signaling in the hippocampus." (PMID 39337316, 2024). "Beyond their apparent involvement in cancer pathology, the anti-inflammatory activity of IGF-1 in mouse models of Alzheimer's disease, or the proliferation of intestinal cells depends also on IGF-1R nuclear signaling." (PMID 39638246, 2024).
Alzheimer disease (continued). "In summary, our study offers valuable transcriptome data for hippocampal and adipose tissues within an Alzheimer’s disease model and posits a significant role for IGF-1 within both the hippocampus and adipose tissue." (PMID 38473814, 2024). "Characterised as IGF-1 resistance, the increase in IGF-1 concentration has been shown in age-related degenerative conditions, such as Alzheimer’s disease and Parkinson’s disease." (PMID 36770687, 2023). "In that review, plasma insulin growth factor-1 (IGF-1) and Alzheimer’s disease (AD)-related biomarkers were found to have a significant role as markers of neurocognitive damage in children with SDB." (PMID 36138586, 2022). "Some relationship between abnormal cholesterol content and impairment of insulin/insulin-like growth factor I (IGF-1) signaling has been reported in the pathogenesis of Alzheimer's disease (AD)." (PMID 34671194, 2021). "In neurodegenerative diseases, such as amyotrophic lateral sclerosis (ALS) and Alzheimer’s disease (AD), the role of GH/IGF-1 has also been reported." (PMID 31967977, 2020). "The insulin/insulin-like growth factor 1 (IGF1) signaling pathways are implicated in longevity and in progression of Alzheimer’s disease." (PMID 30056117, 2018). "Impairment of IGF1 signaling has been demonstrated in Alzheimer’s Disease (AD), particularly in neurons." (PMID 30056117, 2018). "A reduced insulin/IGF-1 signaling in experimental animal model protects the mammalian brain from amyloid-β toxic effects, neurodegeneration, and Alzheimer disease." (PMID 29149058, 2017). "GHRH also increases the level of IGF-1, thereby collectively improving Alzheimer’s disease (AD)-and obstructive sleep apnea (OSA)-related cognitive dysfunction." (PMID 29273763, 2017). "In both Alzheimer’s disease (AD) models and patients, IGF-1 has been suggested to increase Β-amyloid clearance and protect neurons against Β-amyloid toxicity." (PMID 29065116, 2017). "The three transcripts that are similarly misexpressed are Ace, Igf1 and Gfap, strongly related to Alzheimer’s disease." (PMID 26932723, 2016). "A large database of clinical trials is required for better understanding the relationship between IGF-1 levels and Alzheimer’s disease." (PMID 27227831, 2016). "We conducted a meta-analysis to determine the relationship between IGF-1 serum levels and Alzheimer’s disease." (PMID 27227831, 2016). "The complex relationship of IGF-1 with brain function is also reflected in the heterogeneous results from studies in Alzheimer’s disease (AD), a neurodegenerative disorder characterized by declining cognition." (PMID 27115487, 2016). "A significant body of data has identified IGF-1 both as a major regulator of amyloid β-peptide (Aβ) physiology and as an important factor in the pathogenesis of Alzheimer's disease (AD)." (PMID 26417600, 2015). "Disturbances in insulin and possibly insulin growth factor-1 (IGF-1) signaling in the brain, especially the hippocampus, have been observed in Alzheimer’s disease." (PMID 25755673, 2015). "Experimental studies have suggested that the IGF-1 system is beneficial in cognition, especially in Alzheimer’s disease (AD), by opposing Aβ amyloid processing and hyperphosphorylated tau toxicity." (PMID 26702376, 2015). "Accumulating evidence suggests that low levels of circulating IGF-1 and impairments of insulin/IGF-1 signaling in the brain contributed to age-dependent cognitive decline, such as Alzheimer’s disease." (PMID 25247581, 2014). "Another such example is the observation that circulating IGF-1 in centenarians with robust cognition is low, while those suffering Alzheimer's disease (AD) show high levels of this protein in their blood." (PMID 22064828, 2011). "Evidence shows that the insulin-like growth factor-1 (IGF-1) and leptin reduce β-amyloid (Aβ) production and tau phosphorylation, two major hallmarks of Alzheimer's disease (AD)." (PMID 21651786, 2011).
Alzheimer disease (continued). "It was also speculated that serum proteins, such as IGF-1, could be mediating depression symptomatology in patients with Alzheimer’s disease (AD)." (PMID 40141202, 2025). "Resistance exercise could represent an alternative therapy for preventing and treating Alzheimer’s disease, as it has also been shown to have a significant effect on IGF-1 levels—being most effective with three weekly sessions." (PMID 41373296, 2025). "Focusing on the top three studies, the most cited article (“Defects in IGF-1 receptor, insulin receptor and IRS-1/2 in Alzheimer’s disease indicate possible resistance to IGF-1 and insulin signalling”) was published in the Neurobiology of Aging in 2010 and was cited 602 times." (PMID 41017976, 2025). "Hence, our research endeavors to comprehensively explore the impact of IGF-1 on the hippocampus and adipose tissue in the context of Alzheimer’s disease." (PMID 38473814, 2024). "Moreover, the relationship between IGF-1 and cognitive impairment has been widely studied in Alzheimer ́s disease, but offered discrepant results." (PMID 37894932, 2023). "Similarly, Klotho was related to IGF1 signalling inhibition, thus to neuroprotection in Alzheimer’s disease mouse model." (PMID 37985893, 2023). "Besides, IGF-1 has been demonstrated to inhibit the aggregation of amyloid-β protein and the phosphorylation of tau, two hallmarks of Alzheimer’s disease (AD)." (PMID 37608387, 2023). "Consequently, IGF-1 has been a therapeutic candidate against many disorders including Alzheimer’s disease, Fragile X syndrome, Rett syndrome, amyotrophic lateral sclerosis (ALS) and Parkinson’s disease." (PMID 35298717, 2022). "Decreased peripheral and cerebrospinal fluid IGF-1 concentrations could be a potential marker for the cognitive decline and progression of Alzheimer’s disease." (PMID 35631301, 2022). "As IGF-1 is involved in synaptogenesis, increased bioavailable IGF-1/cGP could improve brain function in Alzheimer’s disease." (PMID 35631301, 2022). "In addition to these well-known IGF-1 deficiency conditions and its correlation with aging and cognition, several neurodegenerative disorders show low IGF-1 serum levels, such as PD, Alzheimer’s disease and cerebrovascular disease." (PMID 32046737, 2020). "In this line, previous studies showed that the presence of a risk factor for Alzheimer’s disease, such as high IGF-1 serum levels, does not relate to alterations in specific areas, but rather to global topological rearrangements in the beta and theta bands." (PMID 30737580, 2019). "Knowing the capacity of chronically activated microglia to produce IGF-1 may therefore show essential to promote beneficial microglial functions in Alzheimer’s disease (AD)." (PMID 31417357, 2019). "The primary data analyzed was serum IGF-1 from Alzheimer’s disease subjects and controls." (PMID 27227831, 2016). "The therapeutic potential of IGF-1 has been demonstrated in animal models of a number of neurodegenerative diseases such as cerebellar ataxia, multiple sclerosis and Parkinson disease and Alzheimer disease, in which treatment with IGF-1 alleviates neurological symptoms." (PMID 27483352, 2016). "Systemic IGF-1 therapy improved the cognitive function in mouse models with Alzheimer’s disease." (PMID 27627435, 2016). "Insulin-like growth factor 1 (IGF-1) serum levels have been reported to be altered in Alzheimer’s disease patients, and it was suggested that the changes in IGF-1 serum level may play a role in disease pathology and progression." (PMID 27227831, 2016). "IGF-1 regulates the signaling pathways that are altered in Alzheimer’s disease (AD)." (PMID 27227831, 2016).
Alzheimer disease (continued). "It was shown that higher serum IGF-1 levels in middle age were associated with risk of Alzheimer’s disease in older age, independent of Apolipoprotein E (ApoE) genotype." (PMID 27544533, 2016). "For example, in PD patients with cognitive decline or an additional diagnosis of dementia, IGF-1 levels might show a distinct alteration as suggested by findings showing that IGF-1 levels change differently in Alzheimer's disease (AD) and PD." (PMID 26967642, 2016). "However, by contrast, both IRS-1 and IRS-2 expressions decrease in neurons of humans with Alzheimer’s disease and both insulin and IGF-1 signaling are patently disturbed in brains affected by Alzheimer’s disease." (PMID 25755673, 2015). "IGF-1 therapy has shown potential in models of both Parkinson’s disease and Alzheimer's disease." (PMID 24980976, 2014). "Since deterioration in functional plasticity contributes to the pathogenesis of several brain diseases, IGF-1 arises as a therapeutic strategy to delay the progression and/or to ameliorate the symptoms of neurodegenerative disorders such as Alzheimer's disease." (PMID 22720172, 2012). "Furthermore, insulin and IGF-1-induced signaling is reduced in the brains of patients suffering from Alzheimer's disease (AD)." (PMID 22654904, 2012). "Reduction of insulin/IGF-1 signaling (IIS), a prominent lifespan, developmental and reproductive regulatory pathway, protects worms from proteotoxicity associated with the aggregation of the Alzheimer’s disease-linked Aβ peptide." (PMID 20003171, 2010). "IGFBP3, which is the main binding target of IGF-1, plays an important role in regulating the activity and transport of IGF-1, and was reported to be independently associated with AF in the elderly population in the System-IGF-1 Pathway and Alzheimer’s Disease Clinical Trial (SIGAL)." (PMID 35911532, 2022). "Thus, verifying the effect of physical exercise on cognitive function and IGF-1 levels in people who have progressive cognitive decline, as in Alzheimer’s Disease, may be a promising field for future studies." (PMID 29988330, 2018). "In a series of experiments on mice, a line of human fetal neural stem cells, HK532-IGF-1, reversibly immortalized with c-Myc and modified to increase the expression of IGF-1, was evaluated for the treatment of Alzheimer’s disease." (PMID 37628897, 2023). "There is evidence that insulin-like growth factor-1 (IGF-1) signaling is impaired in PD and Alzheimer’s disease." (PMID 35491799, 2022). "Ten DEGs, including IGF1, VEGFC, RAPGEF3, PIK3CA, Akt3, ITGB3, ITGA11, SPP1, NOS1, and ATP6V0B, were selected from Rap1, oxidative phosphorylation, and Alzheimer’s disease signaling pathways." (PMID 34359260, 2021). "Recently, Schipke and colleagues proposed the combined measurement of six different blood markers, BDNF, IGF-1, VEGF, TGF-beta 1, MCP-1 and IL-18 to identify Alzheimer’s disease patients." (PMID 32098256, 2020). "Expression of neuroprotective genes Igf1, Gpnmb and Spp1 is increased in microglia from both NPC1 and Alzheimer disease mouse models." (PMID 32731618, 2020). "Also, the activation of PI3K by insulin and IGF-1 is markedly disturbed in Alzheimer Disease (AD) brain, leading to sustained activation of Akt, which in turns causes neurons to become increasingly and ultimately totally resistant to both agonists." (PMID 29358916, 2017). "The insulin/IGF1 signalling (IIS) pathways are involved in longevity regulation and are dysregulated in neurons in Alzheimer’s disease (AD)." (PMID 26297026, 2015). "Hence, IGF2 and, to a lesser extent, IGF1 may be effective treatments for Alzheimer's disease." (PMID 25100745, 2014). "Consistent with our results, findings have suggested that IGF1, FLT1, and CD44 may be involved in the development and progression of Alzheimer’s disease and MetS." (PMID 38809924, 2024). "This may be due to the fact that IGF-1 rs972936 is in MDD and Alzheimer's disease plays different roles in the development mechanism." (PMID 35498133, 2022).